ALK (ALK receptor tyrosine kinase)
Diseases named in the same sentence as ALK in open-access papers (continued):
Sharing a sentence is not in itself a finding about the gene and the disease.
esophagitis (1 paper, 2016). An acute or chronic inflammatory disease affecting the esophageal wall. "In summary, this case represents an episode of severe esophagitis secondary to crizotinib therapy for ALK-positive NSCLC, which was provoked by a change in medication administration routine carried out by the patient to accommodate her religious practices." (PMID 28053793, 2016).
esophagogastric junctional adenocarcinoma (1 paper, 2023). "A 66-year-old pre-diseased (CVD, s/p esophagogastric junctional adenocarcinoma) male patient presented with stage IV A ALK-negative, CD30-positive ALCL with lymph node, cutaneous, and pulmonary manifestations, and treatment was initiated with BV-CHP." (PMID 37305564, 2023).
Familial adenomatous polyposis (1 paper, 2017). Familial adenomatous polyposis (FAP) is characterized by the development of hundreds to thousands of adenomas in the rectum and colon during the second decade of life. "Here we report a case of ALK-positive IMT with lymph-node metastasis in the stomach of an adult with a history of familial adenomatous polyposis (FAP)." (PMID 28923119, 2017).
familial cancer (1 paper, 2021). "In contrast to numerous inactivating mutations in tumor suppressor genes, activating mutations contributing to familial cancer are rare and include the genes RET, MET, KIT, and ALK." (PMID 33916261, 2021).
gliosarcoma (1 paper, 2024). A rare histological variant of glioblastoma (WHO grade IV) characterized by a biphasic tissue pattern with alternating areas displaying glial and mesenchymal differentiation (WHO). "Moreover, molecular analysis in some ultra-rare histotypes, such as gliosarcoma, has led to the detection of an ALK alteration in a single case—a finding that had not been previously reported." (PMID 39323465, 2024).
hemangioma (1 paper, 2024). A benign vascular lesion characterized by the formation of capillary-sized or cavernous vascular channels. "Clinically, ALK-rearranged Spitz tumors frequently involve the lower limbs, are often amelanotic, and, for this reason, may be suspected to represent a vascular lesion (hemangioma, etc.), a keloid lesion, a verrucous lesion, xanthogranuloma, or even a melanocytic naevus." (PMID 38390852, 2024).
hereditary gingival fibromatosis (1 paper, 2024). Hereditary gingival fibromatosis (HGF) is a rare benign, slowly progressive, non-inflammatory fibrous hyperplasia of the maxillary and mandibular gingivae that generally occurs with the eruption of the permanent (or more rarely the primary) dentition or even at birth. "To date, genetic variants in five genes, SOS1, REST, ZNF862, ALK, and CD36, have been linked to hereditary gingival fibromatosis." (PMID 39201553, 2024).
hereditary spherocytosis (1 paper, 2022). Hereditary spherocytosis is a congenital hemolytic anemia with a wide clinical spectrum (from symptom-free carriers to severe hemolysis) characterized by anemia, variable jaundice, splenomegaly and cholelithiasis. "This constellation is indistinguishable from hereditary spherocytosis based on standard laboratory tests and resolves after a switch to other ALK TKIs." (PMID 35681698, 2022).
Hyponatremia (1 paper, 2024). An abnormally decreased sodium concentration in the blood. "A postulated explanation attributed hyponatremia in patients treated with ALK inhibitors to inadequate secretion of antidiuretic hormone in the collecting ducts and thus producing hyponatremia." (PMID 39026680, 2024).
intestinal tumor (1 paper, 2025). "The present case exhibited extremely peculiar clinicopathological features and can easily be misdiagnosed as primary intestinal tumors with ALK rearrangement." (PMID 40224190, 2025). "In conclusion, this case exhibited highly unusual clinicopathological features that could easily lead to misdiagnosis as primary intestinal tumors with ALK rearrangement." (PMID 40224190, 2025).
intraductal carcinoma (1 paper, 2021). "Additionally, one intraductal carcinoma showed ALK rearrangement by FISH, in which a hybrid capture–based next generation sequencing identified the exact genomic breakpoint in a novel ALK and the MYO18A gene fusion on chromosome 17." (PMID 33237469, 2021).
intrauterine growth restriction (1 paper, 2021). "In humans, ALK-rearranged NSCLC during pregnancy has been described, and one study reported intrauterine growth restriction in one twin of a dichorionic diamniotic pregnancy after intrauterine exposure to erlotinib, but normal development at 12 months." (PMID 33799824, 2021).
Leber congenital amaurosis (1 paper, 2016). Leber congenital amaurosis (LCA) is a retinal dystrophy defined by blindness and responses to electrophysiological stimulation (Ganzfeld electroretinogram (ERG)) below threshold, associated with severe visual impairment within the first year of life. "Immunohistochemical assays of the epithelial membrane antigen (EMA), S100, vimentin, KI67, creatine kinase (CK), Leber congenital amaurosis (LCA), CD68, antibodies against glial fibrillary acidic protein (GFAP), BCL2, anaplastic lymphoma kinase (ALK), and synaptophysin levels were performed." (PMID 27917338, 2016).
liver failure (1 paper, 2024). A liver disease characterized by the liver losing or has lost all of its function. "Here, we present a case of an ALK fusion‐positive non‐small‐cell lung cancer (NSCLC) patient who developed liver failure due to diffuse liver metastasis at initial diagnosis." (PMID 39527462, 2024). "Here, we report a case of an ALK‐positive NSCLC patient with significant liver metastases and tumor‐induced liver failure at initial presentation." (PMID 39527462, 2024).
malakoplakia (1 paper, 2023). Malakoplakia is a chronic multisystem granulomatous inflammatory disease characterized by the presence of single or multiple soft plaques on various organs of the body. "Here, we report a case of malakoplakia with aberrant ALK expression by immunohistochemistry and discuss its clinical significance." (PMID 37644531, 2023). "Here, we present one case of malakoplakia with aberrant ALK expression by immunohistochemistry and discuss the clinical significance." (PMID 37644531, 2023). "The pathological diagnosis was malakoplakia with aberrant ALK expression by immunohistochemistry." (PMID 37644531, 2023). "There have been no reports of malakoplakia expressing anaplastic lymphoma kinase (ALK) to date." (PMID 37644531, 2023).
malaria (1 paper, 2024). Malaria is a serious and sometimes fatal disease caused by a parasite that commonly infects a certain type of mosquito which feeds on humans. "Although the receptor tyrosine kinase family to which ALK belongs does not exist in malaria, we cannot grossly rule out the possibility that well-active molecules such as 36 also inhibit the function of other P. falciparum kinases or even other ATP-binding proteins." (PMID 38890421, 2024).
malignant pleural mesothelioma (1 paper, 2019). A malignant neoplasm that arises from mesothelial cells in the pleura and shows a diffuse growth pattern. "In malignant pleural mesothelioma, the combination of afatinib and MET/ALK/RON/ROS inhibitor crizotinib has been investigated in cell culture and mouse xenograft models." (PMID 31557260, 2019).
malignant smooth muscle tumors (1 paper, 2025). "Approximately 87.5% to 100% of IMT are ALK-positive, but both benign and malignant smooth muscle tumors are ALK-negative, making IHC with ALK specific for IMT." (PMID 39833069, 2025).
mature T-cell lymphoma (1 paper, 2024). "Cases of EBV+ mature T-cell lymphoma diagnosed as systemic ALK-negative ALCL have been reported in the literature, further complicating the differential diagnosis." (PMID 38921179, 2024).
mediastinal neoplasm (1 paper, 2023). "One patient presented with mediastinal neoplasm without surgical treatment, and progressive disease occurred after two years of ALK inhibitor therapy." (PMID 36915094, 2023).
memory impairment (1 paper, 2021). "All these results point to the critical role played by ALK in the phosphorylation and accumulation of tau and in the associated memory impairment seen in 3xTg-AD mice." (PMID 33452442, 2021). "Injection of an ALK.Fc-lentivirus exacerbated memory impairment in 3xTg-AD mice." (PMID 33452442, 2021).
mesoblastic nephroma (1 paper, 2021). A solid, unencapsulated tumor of the kidney composed of spindle mesenchymal cells that resemble fibroblasts or muscle cells. "For example, in recent years targetable fusions have been identified with high frequency in select pediatric tumors (i.e. NTRK‐fusions in infantile fibrosarcoma and mesoblastic nephromas or ALK/ROS1/NTRK3 fusions in infantile myofibroblastic tumors)." (PMID 33751835, 2021).
myopericytoma (1 paper, 2025). A usually slow growing, subcutaneous nodular neoplasm arising from myopericytes. "Right hemihepatectomy was performed and histopathological examination revealed a well-circumscribed mass consistent with myopericytoma, supported by positive immunohistochemical staining for SMA and H caldesmon, and negativity for Desmin, DOG-1, and ALK." (PMID 40043410, 2025).
nasal polyps (1 paper, 2018). "This suggests that ALK activation might have anti-inflammatory effects on epithelial cells of nasal polyps." (PMID 29367682, 2018). "In addition, polyps demonstrate low levels of Activin A whereas patients with CRSsNP demonstrate high levels of both TGF-β1 and Activin A. These studies indicate that ALK activation, through TGF-β1 and Activin A, is low in nasal polyps and possibly contributing to disease progression." (PMID 29367682, 2018).
night blindness (1 paper, 2013). Inability to see clearly in dim light. "Observations included night blindness in some patients receiving foretinib, other ocular toxicities with crizotinib, a MET/ALK inhibitor, and hematologic toxicities with tivantinib, an inhibitor of MET." (PMID 22918720, 2013).
non-melanoma skin carcinoma (1 paper, 2020). "During the same time period, 100 patients with ALCLs other than ALK-negative and CD30-positive histologic subtypes were identified, representing 0.05% of all malignancies except non-melanoma skin cancers (C44)." (PMID 32344893, 2020).
optic disc edema (1 paper, 2025). "Although uncommon, inflammatory or vascular complications—including optic disc edema with vasculitic leakage—have also been reported, resolving after switching to alternative ALK inhibitors." (PMID 41458610, 2025).
optic nerve disorder (1 paper, 2024). A non-neoplastic or neoplastic disorder affecting the optic nerve (second cranial nerve). "Inhibitors of BCR-ABL1, VEGF, ALK, and proteasomes have all been linked to optic nerve disorders which can have debilitating consequences for vision." (PMID 38345654, 2024).
osteitis (1 paper, 2020). "Here, we report a case of osteitis induced by an ALK inhibitor mimicking bone metastasis, a previously undescribed side effect of crizotinib." (PMID 31906956, 2020). "Crizotinib differs from other ALK inhibitors as it targets other kinases as well, which may have been responsible for the osteitis." (PMID 31906956, 2020).
overgrowth syndrome (1 paper, 2021). A group of syndromes caused by genetic birth defects that may lead to the development of malignancies. "Similarly, the Pan-ALK inhibitor ARQ 092 (Miransertib) showed promising results on a cohort of 6 patients with PIK3CA-Related Overgrowth Syndrome." (PMID 34112235, 2021).
pancreatitis (1 paper, 2022). Inflammation of the pancreas. "A reduced dose of the ALK inhibitor alectinib was administered rather than the standard dose of alectinib or chemotherapy because of recurrent pancreatitis, which has not been previously reported in APH cases." (PMID 35665359, 2022).
parasite infection (1 paper, 2022). "Alternatively, SCG2 and ALK genes associated with coccidian parasite resistance are also actively involved in the MAPK signaling pathway, which has a significant role in immune responses against parasite infection." (PMID 36553445, 2022).
peritoneal disease (1 paper, 2025). "By June 2025, 15 patients are alive without evidence of disease; one patient (Case 11) is alive with controlled peritoneal disease on ALK inhibition." (PMID 40980125, 2025).
primary cutaneous marginal zone B-cell lymphoma (1 paper, 2022). Extranodal lymphoma of lymphoid tissue associated with mucosa that is in contact with exogenous antigens. "We present a case of NSCLC harboring ALK mutation with primary cutaneous marginal zone B-cell lymphoma (PCMZL) treated with adjuvant chemotherapy with pemetrexed and cisplatin, and ALK-echinoderm microtubule-associated protein-like 4 (EML4)-targeting treatment alectinib." (PMID 36348885, 2022).
psychological distress (1 paper, 2025). "For patients with EGFR or ALK mutations, we adopted the MMSE assessment scale, EORTC QLQ-C30 scale, and DT scale to evaluate the relationship between changes in cognitive function during targeted treatment and QoL and psychological distress and cognitive function’s impact on treatment outcomes." (PMID 40966684, 2025).
pulmonary adenoid cystic carcinoma (1 paper, 2015). "The data presented in this work suggest that EGFR, KRAS, BRAF, ALK, PIK3CA, PDGFRA, and DDR2 may not be driver genes in primary pulmonary adenoid cystic carcinoma." (PMID 26373952, 2015).
pulmonary lymphoma (1 paper, 2023). "As a result, L1196M ALK mutation was detected only in the pulmonary lymphoma sample and not in any of the blood samples, including the sample at the second relapse." (PMID 36819147, 2023).
pulmonary mucoepidermoid carcinoma (1 paper, 2024). A lung carcinoma characterized by the presence of malignant non-keratinizing squamoid cells, mucin-producing cells and intermediate type cells. "Pulmonary mucoepidermoid carcinoma (PMEC) is a rare lung malignancy, especially in combination with ALK mutations, whose clinical presentation lacks specificity and for which there are no standardized treatment guidelines." (PMID 39259069, 2024).
salivary gland carcinoma (1 paper, 2021). A carcinoma that arises from the major or minor salivary glands. "A total of 182 salivary gland carcinomas were tested for anaplastic lymphoma kinase (ALK) positivity by immunohistochemistry (IHC) using the cut-off of 10% positive cells." (PMID 33237469, 2021). "Therefore, we systematically evaluated ALK by immunohistochemistry (IHC) followed by dual color fluorescence in situ hybridization (FISH) and new generation sequencing (NGS) in IHC-positive cases in a large, well-characterized series of salivary gland carcinomas." (PMID 33237469, 2021).
sarcomatoid lung carcinomas (1 paper, 2020). "Hence we recommend performing ALK gene rearrangement analysis in all cases of sarcomatoid lung carcinomas." (PMID 32149365, 2020).
signet-ring cell carcinoma of the lung (1 paper, 2018). "Favourable results were seen in one patient with ALK-rearranged signet-ring cell carcinoma of the lung, who presented complete response after WBRT and crizotinib beyond progression (BP) (case 1) and in another patient who had SD after SRS as monotherapy (case 6)." (PMID 29662531, 2018).
small intestine cancer (1 paper, 2025). A primary or metastatic malignant neoplasm involving the small intestine. "Although rare, anaplastic lymphoma kinase (ALK) alterations, which are usually detected in non-small cell lung cancer (NSCLC), have also been identified in small intestinal cancer." (PMID 40160872, 2025).
smooth muscle tumor (1 paper, 2018). A benign or malignant myomatous neoplasm arising from smooth muscle. "Its myxoid differentiation associated with a rearranged and apparently amplified allele of ALK fits with these genetic alterations seen in smooth muscle tumors in general as well as in uterine myelofibroblastic tumors displaying myxoid features and may offer novel options for targeted therapy." (PMID 29963223, 2018).
systemic sclerosis (1 paper, 2020). A chronic disorder, possibly autoimmune, marked by excessive production of collagen which results in hardening and thickening of body tissues. "However, the genes harboring intronic SNPs, ALK (rs4575680), EPHA3 (rs1512909), and TULP4, also known as TUSP (rs341137), have been implicated in CVD-related traits, such as blood pressure, arterial fibrillation, and systemic sclerosis." (PMID 33374401, 2020).
tauopathies (1 paper, 2021). "To assess in vivo effects of ALK on tau-mediated neurodegeneration, we employed a human tau transgenic fly (gl-tau2.1 line), a well-characterized tauopathy model in which human tau is expressed in the photoreceptor neurons." (PMID 33452442, 2021). "Given ALS is largely attributable to the accumulation of the misfolded or aggregated proteins, the ability of ALK to impair autophagy function may also contribute to the pathogenesis of other neurodegenerative diseases as well as tauopathies including AD." (PMID 33452442, 2021).
teratoma (1 paper, 2023). A non-seminomatous germ cell tumor characterized by the presence of various tissues which correspond to the different germinal layers (endoderm, mesoderm, and ectoderm). "In summary, this case represents the first known use of crizotinib to target oncogenic ALK overexpression in central‐type PNET arising from an immature teratoma and highlights the importance of obtaining early molecular analyses in these rare tumor entities to determine novel treatment options." (PMID 36619485, 2023).
thymic tumors (1 paper, 2025). "Similar to NPM::ALK Hdac1KO mice, NPM::ALK dHdac1KI mice exhibited highly accelerated lymphomagenesis and developed thymic tumors with a median survival of 9.4 weeks." (PMID 40175628, 2025). "Notably, T cell-specific deletion of Hdac1 in non-ALK-transgenic mice also induced thymic tumors in approximately a quarter of mice at older ages, whereas no signs of malignant transformation were observed in thymi of mice with a deletion of Hdac2." (PMID 40175628, 2025). "NPM::ALK-transgenic mice developed thymic tumors with a median survival of 17.9 weeks." (PMID 40175628, 2025). "While NPM::ALK transformed T cells showed very low levels of TCRb expression, as previously shown, ALK+ cells from NPM::ALK Hdac1KO and NPM::ALK dHdac1KI tumors exhibited a higher frequency of TCRb+ cells in their thymic tumors." (PMID 40175628, 2025).
xeroderma pigmentosum (1 paper, 2024). Xeroderma pigmentosum (XP) is a rare genodermatosis characterized by extreme sensitivity to ultraviolet (UV)-induced changes in the skin and eyes, and multiple skin cancers. "Notably, we identified four cases (5%) with ALK mutation, all of which were located in sun-exposed areas and had a Breslow index superior to 1.5 mm, and one of the patients had xeroderma pigmentosum." (PMID 39000050, 2024).